CD4 (CD4 molecule)
Diseases named in the same sentence as CD4 in open-access papers (continued):
Sharing a sentence is not in itself a finding about the gene and the disease.
AIDS (continued). "P. jirovecii is an extracellular microorganism that causes life-threatening pneumonia mainly in people living with human immunodeficiency virus infection and acquired immune deficiency syndrome (HIV/AIDS), especially with a CD4+ T-lymphocyte count (CD4) below 200/uL." (PMID 39897288, 2025). "Coinfection with TB and HIV has a bidirectional impact: HIV reduces the CD4 lymphocyte population, which favors the progression and clinical severity of TB, while TB accelerates the progression of HIV to acquired immunodeficiency syndrome (AIDS), increasing associated mortality." (PMID 41179006, 2025). "Talaromyces marneffei (T. marneffei) infection is regarded as a common and indicative opportunistic infection associated with immunosuppression in Southeast Asia, particularly in acquired immunodeficiency syndrome (AIDS) patients with CD4+ T-cell counts less than 200 cells/mL." (PMID 38497717, 2024). "Human immunodeficiency virus type 1 (HIV-1), a member of the Lentivirus genus within the Retroviridae family, is responsible for causing acquired immunodeficiency syndrome (AIDS) by mainly targeting the body’s immune system, including CD4+ T lymphocytes, macrophages, and dendritic cells." (PMID 39199429, 2024). "Acquired immunodeficiency syndrome (AIDS) occurs when HIV depletes CD4+ helper T cells." (PMID 39459974, 2024). "Our findings revealed an increased risk of HIV/AIDS-related mortality and poorer prognosis in older individuals, males, individuals who acquired the infection through injection drug use, individuals with baseline CD4+ T lymphocyte counts of <200 cells/μL, and individuals in WHO clinical stage IV." (PMID 38454987, 2024). "Notwithstanding their strengths, it has been observed that in individuals with CD4 T cell counts below 350 cells/mL or with AIDS-defining events at diagnosis, mutations that result in the failure of this drug class may accumulate, both in treatment-experienced and treatment-naïve patients." (PMID 39364496, 2024). "A higher risk of AIDS and non-AIDS morbidity has also been reported, although an analysis of a large European cohort suggest that this could be completely explained by advanced age, low CD4 counts, and prior comorbidity." (PMID 38500050, 2024). "While current studies indicate that CD4+ T lymphocyte count may not significantly determine surgical outcomes in HIV-infected individuals, a substantial body of research has demonstrated that a low CD4+ T lymphocyte count increases the risk of postoperative complications in HIV/AIDS patients." (PMID 38126075, 2023). "Furthermore, depletion of memory CD4+ T cells, which can be related to either immune activation or by bystander interaction with viral particles rendering the cells more prone to die, is associated with AIDS pathogenesis (3, –, 5)." (PMID 37656815, 2023). "In addition, the prevalence of C. albicans in patients with genetic or acquired immunodeficiency syndrome is increasing, indicating that CD4+T cells are essential to resist C. albicans infection." (PMID 37564654, 2023). "Evidence suggests that high selenium consumption combined with other micronutrients such as vitamin combinations (B vitamins, vitamins C and E) could greatly delay the death of CD4+ cells and the beginning of AIDS, as well as the risk of comorbidities, even though results are still inconsistent." (PMID 37946846, 2023). "Left untreated, HIV-1-infection advances into acquired immunodeficiency syndrome (AIDS) in which the depletion of CD4+ T-cells creates a weakened immune system that allows for opportunistic infections and may eventually lead to death." (PMID 37631062, 2023). "Interestingly, since a low CD4/CD8 T cell ratio is associated with disease progression to AIDS, our results suggest that VX-765 treatment may delay disease progression and preserve CD4+ T cell homeostasis." (PMID 36800238, 2023).
AIDS (continued). "However, control over viremia failed to be maintained by a number of animals during the chronic phase of infection, despite the preservation of IFNγ-producing CD8+ T-cell levels, resulting in increased viral loads, the loss of CD4+ T cells, and rapid progression to AIDS." (PMID 36033843, 2022). "In the pre-highly active antiretroviral therapy (HAART) era, cytomegalovirus retinitis (CMVR) is the most common intraocular opportunistic infection in patients with Acquired Immune Deficiency Syndrome (AIDS) and occurs primarily in patients with an absolute CD4 counts <50 cells/μl." (PMID 35573011, 2022). "Interestingly, there was a significant association between rs1001581 and CD4+ T-lymphocyte count, and the C allele could significantly accelerate the disease progression of AIDS." (PMID 35368687, 2022). "Increased risk of AIDS-specific mortality among people with low baseline CD4 cell count could suggest a reciprocal relationship between hyperglycemia and advanced HIV disease, which should be considered in light of high rates of late HIV diagnosis and serious AIDS-defining conditions in the country." (PMID 36301817, 2022). "HIV type 1 (HIV-1) garnered enormous attention in the 1970s because it can attack CD4 cells and weaken the immune system, eventually causing acquired immunodeficiency syndrome (AIDS) if not suppressed in vivo." (PMID 35054509, 2022). "However, we speculate that progressive loss of CD4+ T cells in AIDS patients can potentially impede clearance of SARS-CoV-2 through its effect on antibody production." (PMID 34843064, 2022). "Acquired Immunodeficiency Syndrome (AIDS) is an acquired defect of the cellular immunity associated with infection by the human immunodeficiency virus (HIV), a CD4 positive lymphocyte count of less than 200 cells/micrometer and increased susceptibility to opportunistic infection." (PMID 36539804, 2022). "In multivariable analyses, lower CD4 count at the last paediatric visit [adjusted hazard ratio = 0.8 (95% confidence interval: 0.7–1.0)/100 cells/μL increment] and AIDS diagnosis in paediatric care [2.7 (1.4–5.5)] were associated with a new AIDS event/mortality in adult care." (PMID 33939876, 2021). "A 30-year-old man with a history of acquired immunodeficiency syndrome (AIDS) (CD4=13 cells/mm3) on antiretroviral therapy for one year presented with truncal weakness for four months, followed by involuntary movement of the right upper and lower limbs and slurred speech a month later." (PMID 34105634, 2021). "Furthermore, there is a clear association between increased risk of death and male sex, low or missing CD4 cell count, prior AIDS, disseminated TB disease, weight loss and MDR-TB; all of which have been found and described in a previous study of the current cohort." (PMID 34615474, 2021). "Such continuous depletion of CD4+ T lymphocytes leads to the acquired immune deficiency syndrome (AIDS) if specific antiretroviral therapy is not addressed promptly." (PMID 34442703, 2021). "The human immunodeficiency virus (HIV-1) is the causative agent of acquired immunodeficiency syndrome (AIDS), characterized by a chronic, progressive depletion of CD4+ T cells, hampering immune function and thus posing vulnerability to opportunistic infections." (PMID 33007800, 2020). "Human immunodeficiency virus (HIV), the causative agent of AIDS, contains two heavily glycosylated envelope proteins, gp120 and gp41, and it has been reported that an interaction between glycoprotein gp120 and the cellular protein CD4 is required to initiate the infection cycle." (PMID 32260400, 2020). "Hence, the effect of CD4 levels on the risk of AIDS was quite direct." (PMID 31996148, 2020). "Hence, BALB/c mice may provide a more appropriate model for declining immunity seen in HIV-AIDS patients where loss of CD4 cells is associated with emergence of opportunistic infections." (PMID 32669460, 2020).
AIDS (continued). "Similarly, CD4+ T cell counts are inversely associated with SD risk and severity in AIDS patients." (PMID 31396143, 2019). "In a similar literature, Imane Zai et al23 have ever investigated the association of IL28B variation and CD4+T count in AIDS individuals, and they came to a decision that rs12979860 polymorphism may affect the response to treatment as measured by CD4+ T cell counts." (PMID 30632263, 2019). "Decreased PD-1 expression on CD4+ T cells among high responders was also associated with an increase of sDDP4 activity in serum (p = 0.014 at week 24), a systemic surrogate marker that strikingly predicts time to AIDS,26–28 as compared to the other groups or the placebo." (PMID 31231551, 2019). "It is straightforward to hypothesize that such a time-varying confounding can also be time-modified, which means not only the confounder (CD4 count) change over time but also its association with the treatment and its impact on the outcome (progression to AIDS) varies during these times." (PMID 31619986, 2019). "Additionally, “unmasking” Toxoplasma-associated IRIS may develop in AIDS patients with low CD4+ T cell numbers, newly established anti-retroviral therapy and unrecognized TE at the beginning of retroviral treatment." (PMID 30873157, 2019). "However, the present patients generally had a long history of exposure to HIV and ART and included numerous cases of severe previous immunodepression (AIDS stage and/or low CD4 nadir), VF, toxicity associated with antiretroviral drugs, and even a previous non suppressive ART." (PMID 30819101, 2019). "Notably, a recent diagnostic accuracy study conducted in 2 Ugandan HIV/AIDS clinics showed that point-of-care CRP screening of HIV-infected people with CD4 counts <351 cells per μL who were initiating antiretroviral therapy yielded 89% sensitivity and 72% specificity for culture confirmed TB." (PMID 30990820, 2019). "In addition, the lower CD4 counts may explain the greater risk of disease development and risk of progression to AIDS, reported to occur more rapidly in Yunnan compared to other regions." (PMID 30998710, 2019). "At late stages of infection, which are characterized by high viral load and low CD4+ T-cell counts in the blood, the patient becomes susceptible to infection with secondary pathogens, such as Pneumocystis carinii, Candida albicans, and Mycobacterium tuberculosis, eventually succumbing to AIDS." (PMID 30619232, 2018). "In multivariate analysis, recent HIV diagnosis (aOR = 2.0, 95% CI: 1.0–3.9), CD4<200 cells/μl (aOR = 4.0, 95%CI: 1.9–8.1), persistent fever (aOR = 4.4, 95%CI: 2.1–9.0), duration of symptoms≥ 6 weeks (aOR = 2.6, 95%CI: 1.2–5.4) were associated with AIDS-defining events." (PMID 30161228, 2018). "The mechanism whereby spherules and/or endospores are killed in vivo is also unknown but must depend indirectly on CD4+ T cells as there is an inverse correlation between the total CD4 count and the risk of disseminated coccidioidomycosis in patients with AIDS." (PMID 30179067, 2018). "Furthermore, it is unknown whether DnaK vaccine-induced lung-resident IL-17+ CD4+ T cells could persist during long-term CD4 deficiency, as in the setting of untreated AIDS." (PMID 29473022, 2018). "Absolute cell counts have been shown to be a major tool for laboratory diagnosis for a variety of pathological conditions, including CD4+ T-cells for Acquired ImmunoDeficiency Syndrome and haematopoietic progenitor cells expressing CD34 for cord blood transplants and autotransplantation." (PMID 30240448, 2018). "Hence, bystander apoptosis is believed to be one of the major causes of CD4 loss leading to AIDS." (PMID 28829402, 2017). "HIV-1 infection is associated with progressive CD4 T cell loss and immune dysfunction caused by several mechanisms such as chronic T cell activation, chronic antigen presentation and dysregulated immune cell homeostasis, which can lead to acquired immunodeficiency syndrome (AIDS)." (PMID 25658330, 2015).
AIDS (continued). "The reason for lack of association between lipid parameters in our cohort of HIV/AIDS patients and the immune status may be related to the close similarity in the CD4+ T cell count as most patients were in the CD4+ T cell count range 200–499 cells/μl and above." (PMID 26315756, 2015). "Thus, unfavorable IL7R genotypes (rs6897932 CC, rs987106 TT, and rs3194051 AA) could lead to an increased risk of severe liver disease, by decreasing CD4+ cells count and enhancing AIDS progression in HIV/HCV coinfected patients." (PMID 26123260, 2015). "The aim of the present study was to assess whether immune-recovery during virological successful HAART among late-presenters (i.e., patients with pre-HAART CD4+ count <200 cells/μl) is associated with the risk of severe non-AIDS related morbidity and mortality, independently of possible confounders." (PMID 26020949, 2015). "Commencement of ART at a baseline CD4 cell count <200 cells/μl may lead to a high proportion of patients with acquired immunodeficiency syndrome (AIDS) and a high case fatality rate." (PMID 25816222, 2015). "In established HIV infection, lower hemoglobin levels have been shown to correlate with decreasing CD4+ T cell counts which is supported by many studies demonstrating an association between anemia during established infection and a faster progression of AIDS as well as death." (PMID 25878898, 2015). "For example, individuals with very low CD4+ (Th) cell counts (i.e., HIV/AIDS) are at much higher risk of opportunistic infections such as Pneumocystis jiroveci pneumonia, mycobacterial infection and toxoplasmosis than those with a higher number of CD4+ T cells." (PMID 27417487, 2014). "However, a high MOI may often result in bystander death of CD4+ lymphocytes, a hallmark of AIDS pathogenesis." (PMID 24586176, 2014). "Factors besides ID and current CD4 count significantly associated with the risk of developing the composite endpoint in the main analysis included older age, a diagnosis of anaemia prior to baseline, previous non-AIDS, and current use of antiretroviral treatment consisting of less than 3 drugs." (PMID 24498036, 2014). "In HIV infected individuals and SIV infected rhesus macaques, a rapid and severe depletion of intestinal CD4+ T cells, in particular of those belonging to the Th17 subset, associates with loss of mucosal integrity, increased immune activation/inflammation, and progression to AIDS." (PMID 25340778, 2014). "The 12-month AIDS risk, which was calculated using the age and the CD4 lymphocyte count, was strongly associated with mortality, suggesting that this parameter could be useful to calculate the level of immunodeficiency in children from resource-limited settings." (PMID 24688879, 2014). "Indeed, 39% of women in MTN-009 had CD4+ T cell counts qualifying them for ART (<350 cell/mm3), and 12.5% women had CD4 counts low enough to increase risk of AIDS (<200 cells/mm3), suggesting either a long duration of unrecognized infection or denial of or unwillingness to report one’s HIV status." (PMID 23585827, 2013). "Notably, the VDR-BB genotype was correlated with more rapid progression to both CD4 counts <200 cells/uL and acquired immunodeficiency syndrome (AIDS)." (PMID 24278668, 2012). "Importantly, the early NAb response is subsided by successive escape of virus from autologous antibodies for continued high-level of virus replication towards progressive destruction of CD4+ T cells, development of acquired immunodeficiency syndrome (AIDS)." (PMID 22606344, 2012). "Chronic HIV infection affects both quantitative and qualitative function of CD4+ T-lymphocytes, and disease progression results from continuous depletion of these cells with a concomitant increase in risk for opportunistic infections, acquired immune deficiency syndrome (AIDS), and death." (PMID 21738861, 2011).
AIDS (continued). "To investigate further possible reasons for declining selection pressure withinGag epitopes with progression to AIDS, we considered the hypothesis that loss ofCD8+ T-cell responses as CD4 count declines results in reversion of escapemutants, with resulting increase in viral replicative capacity." (PMID 21544209, 2011). "Taken together, these data imply that in patients starting cART at low baseline CD4 T-cell counts, numerous pathogenic mechanisms may collectively work to slow their increase in CD4 T-cell numbers and prolong their risk of acquiring AIDS and non-AIDS defining illnesses." (PMID 21674057, 2011). "Nevertheless, the findings of this study strongly suggest that knowledge of the current CD4 cell count and an assessment of other established risk factors for progression to AIDS are sufficient when deciding whether to initiate cART in symptom-free HIV-positive patients." (PMID 20186270, 2010). "Although further studies are required to define the contribution of autoantibodies to AIDS pathogenesis, our study suggests that such antibodies may act in concert with other mechanisms of CD4+ T cell loss, such as immune activation induced cell death and destruction of the lymphoid architecture." (PMID 19360097, 2009). "When a person has been infected with HIV for a long time, the number of CD4 cells they have goes down, resulting in acquired immune deficiency syndrome (AIDS), in which the person's immune system no longer functions effectively." (PMID 19823569, 2009). "It has been shown that viruses binding to CCR5 are almost exclusively present during the early asymptomatic stage of the infection whereas CXCR4-binding viruses may emerge in later phases of the infection and are associated with a CD4+ T-cell decline and progression towards AIDS." (PMID 19816596, 2009). "Results of these analyses indicated that knowledge of the CCL3L1-CCR5 GRG status may improve the ability to predict AIDS risk, especially by identifying those subjects whose CD4 and viral load parameters may incorrectly predict a contrary risk of developing AIDS." (PMID 18776933, 2008). "Furthermore, although a CD4+ T cell count and plasma viral load provides an excellent snapshot of the immunological and virological status of the infected host at the time of their clinical assessment, they are imperfect surrogates of AIDS risk." (PMID 18776933, 2008). "The role of this receptor in the pathogenesis of AIDS has received a lot of attention because it has been shown that high levels of PD-1 expression correlate with declining CD4+ T cell counts and disease progression and are associated with reversible dysfunction of CD4+ and CD8+ T cells." (PMID 18636106, 2008). "We present the case of a 58-year-old male with AIDS (CD4 111 cells/mm3) who developed fevers, seizure-like activity, and septic shock." (PMID 41869129, 2026). "At the time of the study, ART was recommended for individuals with an AIDS-defining illness or with a CD4+ T cell count ≤ 500 cells/mm3." (PMID 39602010, 2026). "This retrospective study evaluated the prognostic value of bronchoalveolar lavage fluid (BALF) CMV DNA loads in 189 AIDS patients with pulmonary infections and CD4+ T cell counts < 200 cells/μL." (PMID 42075704, 2026). "People living with HIV (PLHIV) who are virally suppressed on antiretroviral therapy (ART) experience faster increases in CD4+ cell counts and, therefore, lower mortality, lower rates of progression to AIDS and lower rates of non‐AIDS‐defining cancers." (PMID 41555785, 2026). "Between 1985 and 2024, Romania recorded 28,793 cases of HIV, with 18,881 AIDS cases (at least one AIDS related disease or CD4 levels less than 200 cell/mm3)." (PMID 41562664, 2026). "Participants who were HBeAg-negative and participants who were HBeAg-positive and already on ART before starting tenofovir had higher CD4 counts, CD4 nadir, and were less likely to have experienced an AIDS-defining condition." (PMID 41551412, 2026).